GPR155 (G protein-coupled receptor 155)
Description:
Cholesterol-binding protein that acts as a regulator of mTORC1 signaling pathway. Acts as a sensor of cholesterol to signal cholesterol sufficiency to mTORC1: in presence of cholesterol, binds cholesterol, leading to disruption of the interaction between the GATOR1 and KICSTOR complexes and promotion of mTORC1 signaling. Upon cholesterol starvation, GPR155/LYCHOS is unable to perturb the association between GATOR1 and KICSTOR, leading to mTORC1 signaling inhibition. Binds indole-3-acetic acid and may play a role in tryptophan metabolism.
Synonyms: LYCHOS; PGR22; DEP.7; DEPDC3; FLJ31819
Tractability: Small molecule: a structure with a bound ligand is known. Antibody: UniProt predicts a signal peptide or a membrane-spanning region. PROTAC: ubiquitination databases record sites on it; its protein half-life has been measured.
Gene: Protein-coding gene on chromosome 2 (174,431,571 to 174,487,150, reverse strand). Ensembl gene ENSG00000163328.
Subcellular location: Lysosome membrane
Gene Ontology:
Molecular function: cholesterol binding
Biological process: cellular response to amino acid starvation; cellular response to cholesterol; cognition; positive regulation of TORC1 signaling; negative regulation of BMP signaling pathway; intracellular signal transduction; transmembrane transport
Cellular component: extracellular exosome; lysosomal membrane; membrane
Genetic constraint (gnomAD): Loss-of-function variants: 31 observed, 46.94 expected, observed/expected ratio (o/e) 0.66, 90% interval 0.5 to 0.89. The upper end of that interval is the gene's LOEUF score, 0.89, which puts it in group 3 of 6, group 1 being the genes least tolerant of losing a copy. Missense variants: 601 observed, 745.46 expected, observed/expected ratio (o/e) 0.81, 90% interval 0.75 to 0.86. Synonymous variants: 230 observed, 272.87 expected, observed/expected ratio (o/e) 0.84, 90% interval 0.76 to 0.94.
Homologues: Orthologues: chimpanzee GPR155 (99% identical), macaque GPR155 (98% identical), dog GPR155 (94% identical), rabbit GPR155 (93% identical), guinea pig GPR155 (93% identical), pig GPR155 (90% identical), mouse Gpr155 (90% identical), rat Gpr155 (89% identical), tropical clawed frog gpr155 (66% identical), zebrafish gpr155a (52% identical), zebrafish gpr155b (48% identical), Drosophila melanogaster anchor (34% identical). Paralogues in human: PREX1 (18% identical), PREX2 (18% identical), DEPTOR (7% identical).
Diseases named in the same sentence as GPR155 in open-access papers:
GPR155 is named in the same sentence as 21 diseases in open-access papers, as found by Europe PMC text mining. Sharing a sentence is not in itself a finding about the gene and the disease. The quoted sentences say what the papers report.
autism (3 papers, 2009 to 2022). Persistent deficits in social interaction and communication and interaction as well as a markedly restricted repertoire of activity and interest as well as repetitive patterns of behavior. "GPR155 encodes G protein-coupled receptor 155, and reported that mutations in this gene may be associated with autism." (PMID 35402275, 2022). "In a recent study of those with FXS and autism and in those with autism secondary of a 15q duplication, there was abnormal expression of GPR155 (G protein coupled receptor 155) in both groups which is a gene regulated by CYFIP1." (PMID 22043169, 2011).
gastric cancer (3 papers, 2017 to 2022). A primary or metastatic malignant neoplasm involving the stomach. "Although there has been a report that GPR155 expression is suppressed in neoplasm of the thyroid, hepatocellular carcinoma, and gastric cancer, implying a tumor suppressive function for this gene, the resistant role in lung cancer, however, was not reported." (PMID 35402275, 2022). "Consistent in our study, the expression of GPR155 was downregulated in gastric cancer tissue of the ACRG cohort." (PMID 35096829, 2021).
Huntington disease (2 papers, 2017 to 2022). Huntington disease (HD) is a rare neurodegenerative disorder of the central nervous system characterized by unwanted choreatic movements, behavioral and psychiatric disturbances and dementia. "Further, the Gpr155 dysregulation was confirmed in the R6/2 mouse (model system of Huntington’s disease), where it was dysregulated in the striatum-enriched transcripts." (PMID 35897663, 2022). "Originally, Gpr155 (G-protein-coupled receptor 155) was identified in Huntington’s disease patients, where it was reported to be downregulated in the caudate nucleus, suggesting involvement in pathophysiological mechanisms affecting specific brain structures." (PMID 35897663, 2022). "There have been some reports of GPR155 expression in mouse models, such as aberrant expression of GPR155 in UV-induced melanoma and Huntington’s disease models." (PMID 28863781, 2017).
neoplasm of the thyroid (2 papers, 2017 to 2022). "With respect to human neoplasms, only one microarray analysis indicated suppression of GPR155 in thyroid tumor, and to our best knowledge this study is the first to evaluate GPR155 expression in digestive cancers, including HCC." (PMID 28863781, 2017). "Although there has been a report that GPR155 expression is suppressed in neoplasms of the thyroid, the oncologic roles of GPR155 in HCC remain unclear." (PMID 28863781, 2017).
type 2 diabetes (2 papers, 2014 to 2016). "Moreover, not only rare variant SNPs (in the Gpr155) but also common variants (in the Itga6, Zak, and Mtx2) could be candidate genes for type 2 diabetes caused by the gene-gene interaction." (PMID 24789282, 2014). "DEPDC3 has no related literature in PubMed, but it is also known as the G-protein-coupled receptor 155 (Gpr155), which is conserved among mammals and may be a candidate gene for type 2 diabetes in mouse models." (PMID 28000796, 2016).
autism spectrum disorder (1 paper, 2017). A spectrum of developmental disorders that includes autism, and Asperger syndrome. "GPR155 is dysregulated in lymphoblastoid cells in males with autism spectrum disorders (ASDs) relative to their non-affected siblings, suggesting that the gene is associated with ASD." (PMID 29321746, 2017).
chronic hepatitis (1 paper, 2017). An active inflammatory process affecting the liver for more than six months. "GPR155 mRNA expression levels in non-cancerous tissues were comparable among patients with normal liver, chronic hepatitis, and cirrhosis." (PMID 28863781, 2017).
Cirrhosis (1 paper, 2017). A chronic disorder of the liver in which liver tissue becomes scarred and is partially replaced by regenerative nodules and fibrotic tissue resulting in loss of liver function. "GPR155 mRNA expression levels were equivalent among normal liver, hepatitis, and cirrhosis as background liver status." (PMID 28863781, 2017).
colorectal cancer (1 paper, 2022). A primary or metastatic malignant neoplasm that affects the colon or rectum. "GPR155 I357S mutation in lung cancer and ADAMTS20 S1597P and TTN R7415H mutations in colorectal cancer were frequently detected at the time of acquired resistance." (PMID 35402275, 2022). "In addition, the GPR155 I357S mutation in lung cancer and ADAMTS20 S1597P and TTN R7415H mutations in colorectal cancer were frequently detected at the time of acquired resistance, indicating that these mutations have an important function in acquired resistance to chemotherapy." (PMID 35402275, 2022).
lung carcinoma (1 paper, 2022). "GPR155 mutation was frequently detected in acquired resistance time point in lung cancer patients only in the EGFR-TKI treated group." (PMID 35402275, 2022). "Hence, it is worthwhile to further investigate the mechanistic roles of GPR155 I357S mutation in drug resistance of lung cancer patients especially EGFR-TKI." (PMID 35402275, 2022).
metastasis (1 paper, 2017). The spread or migration of cancer cells from one part of the body (where they first appeared) to another. "The clinicopathological factors associated with reduced GPR155 expression reported here conflict with known risk factors for peritoneal dissemination and are, however, associated with known risk factors for hepatic metastasis." (PMID 28165032, 2017).
cancer (5 papers, 2017 to 2024). A tumor composed of atypical neoplastic, often pleomorphic cells that invade other tissues. "GPR155 has also been linked to a number of different cancers." (PMID 35901096, 2022). "In both GC cell lines, GPR155 knockdown led to significant increases in cell proliferation and invasion, indicating that GPR155 has downstream effect to cancer-related signaling pathways and therefore acts as a tumor suppressor." (PMID 28165032, 2017). "The key gene GPR155 in the blue module has also been extensively studied in cancers." (PMID 35096829, 2021). "The presence of GPR155 in multiple gene pairs suggest it might be a crucial regulatory gene in GC and this offers clues for carrying out its further research in cancers." (PMID 35096829, 2021). "We then performed copy number analysis to explore an alternative mechanism of GPR155 transcription because analysis of copy number variations on a genomic scale has been reported to be useful for assessing cancer progression and identifying congenital genetic abnormalities." (PMID 28863781, 2017).
tumor (4 papers, 2017 to 2023). "GPR155 mRNA was suppressed in GC cell lines, and expression level of GPR155 in GC individuals were associated with distant metastasis and tumor recurrence." (PMID 37702614, 2023). "This study was limited by its lack of sufficient functional analysis of GPR155, which tempers the conclusion that it acts as a tumor suppressor in HCC." (PMID 28863781, 2017).
GPR155 also shares sentences with these, for which no sentence is quoted: hepatocellular carcinoma (2 papers); cyst (1); Hepatitis (1); MALT lymphoma (1); melanoma (1); papillary thyroid carcinoma (1); schizophrenia (1); thyroid (1).